CDKN2A (cyclin dependent kinase inhibitor 2A)
Diseases named in the same sentence as CDKN2A in open-access papers (continued):
Sharing a sentence is not in itself a finding about the gene and the disease.
glioma (continued). "In the present study, we used multiple newly implemented techniques to investigate some of the genetic alterations in IDH1, IDH2, CDKN2A, MYB and MYBL1 in pediatric low-grade gliomas." (PMID 35574540, 2022). "Among the 1,004 glioma patients in the MSKCC datasets, 27% patients had EGFR alteration and 33% patients had CDKN2A deletion." (PMID 33959491, 2021). "A previous report indicated that five of seven pediatric grade II–IV astrocytomas with BRAFV600E had concomitant CDKN2A HD and CDKN2A deletions combined with BRAFV600E alterations, constituting a subgroup of secondary high-grade gliomas." (PMID 33980169, 2021). "We found that in adult glioma patients, BRAFV600E and BRAFnon-V600E frequently co-occurred with CDKN2A HDs combined with CDKN2B HDs, especially in patients with BRAFV600E." (PMID 33980169, 2021). "Our analysis of a subset of astrocytoma cases within The Cancer Genome Atlas (TCGA) glioma dataset showed similar results with mutual exclusivity between CDK4 and CDKN2A alterations in all except one case." (PMID 32640746, 2020). "In this study, 47.6% of glioma patients were detected ctDNA including 1p/19q, MDM2, ERBB2, IDH1, CDKN2A, CDK4, PDGFRA, CCNE1, MET." (PMID 32973641, 2020). "Apart from ependymoma, homozygous deletions of CDKN2A have recently been described as adverse prognostic marker for other CNS tumors, including anaplastic IDH-mutant gliomas and BRAF-mutant low-grade gliomas." (PMID 32514758, 2020). "For many years prior to the application of routine next-generation sequencing (NGS) of brain tumors, CDKN2A status was evaluated by FISH as part of the standard evaluation of newly-diagnosed and recurrent gliomas at our institution." (PMID 33081848, 2020). "Finally, given that CDKN2A mutations have been linked to a worse prognosis and a high likelihood of malignant progression, CDK4/6 inhibitors, which are currently used in breast cancer and have been studied in glioblastoma, can also be of interest in the treatment of patients with IDH-mutant gliomas." (PMID 32444979, 2020). "The first germline studies identified a locus on chromosome 9p21, encompassing the CDKN2A (MIM number 600160) and CDKN2B (MIM number 600431) tumor suppressor genes, which have an established role in glioma development." (PMID 31968687, 2020). "By performing a systematic analysis of the CNV-driven ceRNAs with clinical features, we found that the CNVs of some genes (such as MTAP/CDKN2A/CDKN2B/KLHL9) had significant impacts on histological diagnosis and survival in glioma." (PMID 31719831, 2019). "Deletions at 9p21 abrogating the CDKN2A/B and MTAP loci were rare in grade I gliomas (12.2%, p = 0.0178) but frequent in grade IV gliomas (62.5%, p = 0.0087)." (PMID 30558563, 2018). "In secondary high glade gliomas, BRAF V600E and CDKN2A deletion were as high as 39% and 57%, respectively." (PMID 29152094, 2017). "Although IDH-mutant gliomas had lower RB1 expression along with higher methylation, the expression of RB pathway genes CDKN2A and CDKN2B was maintained." (PMID 27852048, 2017). "While genetic alterations such as EGFR amplification and CDKN2A deletion are common in IDH1 WT gliomas, they rarely occur in gliomas with mutant IDH1." (PMID 28178660, 2017).
glioma (continued). "Higher grade pediatric gliomas demonstrate constitutive MAPK activity, but this is almost always accompanied by homozygous deletion of the cyclin-dependent kinase inhibitor 2A (CDKN2A) locus." (PMID 25821557, 2015). "Looking into well-known oncogenes and TSGs, we identified gains of EGFR in “de novo glioma pathway” (2 in LGG and 3 in HGG), as well as MDM2 (1 in LGG and 3 in HGG) and PTEN (1 in HGG), and losses of CDKN2A (2 in HGG)." (PMID 23451178, 2013). "We also detected the expression of CDKN2A in high (T98G, U251-MG, U87-MG, A172, SW1736, U118-MG and U138-MG) and low grade glioma cells (H4 and HS-683)." (PMID 21843312, 2011). "All three high grade lines had highly complex genomic profiles and harboured amplifications and deletions at several known cancer genes dysregulated in paediatric glioma, including CCND1, MYC, CDK4, PIK3CA, CDKN2A/B, and RB1." (PMID 19365568, 2009). "Survey of a panel of 747 human cancer cell lines of 32 anatomical origins for genomic status of CDKN2A (p16INK4A and p14ARF) and CDKN2C revealed that codeletion of these two loci was observed predominantly in glioma tumor cell lines." (PMID 18394558, 2008). "The prognosis of gliomas is significantly affected by these molecular alterations, such as whether IDH1, IDH2, EGFR, CDKN2A, and CDKN2B are altered for adult‐type gliomas, and whether H3 K27 and H3 G34 are altered for pediatric‐type gliomas." (PMID 39804195, 2025). "Similarly, the favor prognosis of TERT promoter mutation in CDKN2A/B none homozygous deletion IDH mutant adult‐type gliomas, which the difference with the CDKN2A/B homozygous deletion group may be caused by the limited number of CDKN2A/B homozygous deletion group." (PMID 39804195, 2025). "It has also been used to detect complex CNVs such as JAK1-PAK2, JAK1-PVT1, JAK1-MYOCD, JAK1-TIMM21, USP7-TIMM21, and JAK1-Chr22 CNVs in whole blood-derived ovarian cancer samples, EGFR, CDKN2A, and BRAF CNV in glioma tissues, as well as FGFR2 CNV in colorectal and gastric adenocarcinomas." (PMID 40725150, 2025). "Finally, we selected the following seven indicators as the mIHC panel: IDHR132H, ATRX, EGFR, CDKN2A, HIP1R, GFAP (glial fibrillary acidic protein, marker of glioma cells), and DAPI (4ʹ,6‐diamidino‐2‐phenylindole, marker cell nucleus)." (PMID 40264576, 2025). "According to the 2021 updates, molecular characteristics such as CDKN2A/B homozygous deletion now play a major role, leading to the reclassification of a subset of IDH-mutant low-grade gliomas as grade 4 tumours, reflecting a more aggressive biological profile." (PMID 40136387, 2025). "Our results showed that BRAF V600E mutation, alone or in combination with CDKN2A homozygous deletion, did not have a significant impact on PFS in pediatric patients with high-grade glioma." (PMID 40860828, 2025). "For example, the presence of a homozygous deletion of CDKN2A necessitates classifying the glioma as grade 4, regardless of histopathological data." (PMID 39135755, 2024). "More specifically, if patients with CNS WHO grade 4 glioma do not have CDKN2A deletion, they have longer PFS and OS than those with a CDKN2A deletion, regardless of the presence of IDH mutation." (PMID 39457569, 2024). "This recommendation does not extend to IDH-mut ODG that are neuropathologically consistent with CNS WHO grade 2 gliomas, as these typically do not have the CDKN2A/B homozygous deletion." (PMID 39593128, 2024). "Genetic aberrations associated with worse prognoses, such as PDGFRA amplification, CDKN2A or CDKN2B deletion, and CDK4 amplification, may lead to further glioma subdivision." (PMID 38672625, 2024). "Median OS in patients with IDH-mut gliomas without CDKN2A/B deletion was 92.0 months compared to 40.0 months with CDKN2A/B deletion (p < 0.001, Log-Rank)." (PMID 39593128, 2024). "In the present study, clinical data analysis did not confirm a significant correlation between CDKN2A deletion and other gene mutations in CNS WHO grade 4 gliomas." (PMID 39457569, 2024).
glioma (continued). "According to a study including 230 glioma cases, among 9p21 deleted cases 10% had CDKN2A HD without MTAP HD." (PMID 38109891, 2024). "The lack of evidence showing the biological mechanism of CDKN2A deletion in affecting the prognosis of patients with CNS WHO grade 4 glioma makes a comprehensive study mandatory." (PMID 39457569, 2024). "And Imnecrosis was significantly more identified in IDH-wildtype, 1p19q-non-codeletion, and CDKN2A/B-homozygous-deletion gliomas." (PMID 38378035, 2024). "We further introduce a segmented block bootstrapping approach to detect focal alternations that achieved 60.9% sensitivity and 98.6% specificity for deletions affecting CDKN2A/B (60.0% and 96.9% for RB1, respectively) in a low-grade glioma cohort from TCGA (n = 239 samples)." (PMID 38244574, 2024). "Many roles for CDKN2A/B homozygous deletion as a negative prognostic factor have been reported for IDH-mutant low-grade gliomas." (PMID 39457569, 2024). "Previous studies have shown that the CDKN2A homozygous deletion is an important prognostic factor for survival outcomes of IDH-mutant glioma patients regardless of histology grading." (PMID 39108689, 2024). "Even if CNS WHO grade 4 gliomas have mutant IDH1/2, they may have poor clinical outcomes because of CDKN2A deletion." (PMID 39457569, 2024). "This new classification diagnoses gliomas not solely based on histology, but complemented by more sophisticated molecular markers such as CDKN2A which is important for IDH-mutant gliomas." (PMID 38135704, 2023). "They observed that CDKN2A deletions were negative prognostic indicators of survival in all 135 gliomas, but this was not seen when stratifying for grade 3 or 4 separately." (PMID 37504251, 2023). "The authors analysed 270 gliomas and identified CDKN2A deletions via FISH in 57/108 grade 2 astrocytomas, 31/61 grade 3 astrocytomas, 23/96 oligodendrogliomas, and 19/49 oligoastrocytomas, inclusive of both homozygous and heterozygous CDKN2A deletions." (PMID 37504251, 2023). "Here, we describe the correlation between p16 IHC expression and CDKN2A heterozygous and homozygous deletion assessed by FISH in a cohort of low- and high-grade diffuse pediatric- and adult-type gliomas, as well as in circumscribed gliomas." (PMID 36900302, 2023). "Sixty-eight percent (38/56) of gliomas with an absence of p16 expression demonstrated a CDKN2A homozygous deletion on FISH assays." (PMID 36900302, 2023). "It comprises genetic features of the proneuronal glioma subtype by combining PDGFB amplification with the lack of cell cycle regulator Cdkn2a." (PMID 36358353, 2022). "However, in recent years, many molecular and genetic biomarkers have been identified as noninvasive factors in the diagnosis of gliomas, including glutamate, ATIA, cathepsin D, GADD45, YKL40, Ki67, MIP-1, and CDKN2A." (PMID 35053475, 2022). "In our longitudinal analysis of three paired initial and recurrent or metastatic high-grade gliomas, the key genetic drivers (e.g., NF1, CDKN2A, ATRX) were shared truncal events while only chromosomal copy number aberrations were private to initial or recurrent/metastatic tumors." (PMID 35945463, 2022). "In glioma samples with high LYN expression, oncogenic driver genes such as EGFR (7p11.2) and CDK4 (12q14.1) were frequently amplified, while tumor suppressor gene PTEN (10q23.31) and CDKN2A (9p21.3) were frequently deleted." (PMID 35186945, 2021). "Concerning specific drivers of glioma progression, recurrent IDH mutant-noncodel gliomas presented an enrichment in CDKN2A homozygous deletions, with subsequent DNA aneuploidy and genetic instability that were associated with shorter OS." (PMID 33673104, 2021). "The presence of a homozygous deletion of cyclin-dependent kinase inhibitor 2A/B (CDKN2A/B) is now playing an important role in glioma classification as a negative prognostic biomarker." (PMID 34638714, 2021). "One hundred and sixty-one glioma patients had both EGFR and CDKN2A alterations." (PMID 33959491, 2021).
glioma (continued). "Interestingly, CDKN2A and EGFR are converged on cell cycle regulation and both are altered in the early stage of glioma development." (PMID 33959491, 2021). "Moreover, the ctDNAs in the metastatic brain tumors included ALK and MDM2, and glioma-related ctDNAs included 1p/19q and MDM2 followed by frequencies of ERBB2, IDH1, CDKN2A, CDK4, PDGFRA, CCNE1, MET." (PMID 32973641, 2020). "Glioma-related ctDNAs included 1p/19q, MDM2, ERBB2, IDH1, CDKN2A, CDK4, PDGFRA, CCNE1, MET." (PMID 32973641, 2020). "From the analysis above, we observed that several cell cycle related genes, such as CDKN2A/2B (14% vs. 3%), CDK4 (10% vs. 0) and RB1(10% vs. 0), were dominant in recurrent gliomas as compared to primary gliomas, so we further clustered the mutated genes according to their functional characteristics." (PMID 31690770, 2019). "It has been shown that the deletion of 9p21, especially co-deletions of CDKN2A/B and MTAP, could be a marker for different grades of glioma." (PMID 31719831, 2019). "In contrast, copy number analysis of her DIPG revealed copy number changes frequently seen in gliomas including homozygous loss of RB1, SETDB2, CDKN2A and CDKN2B with no abnormalities in chromosome 17, distinguishing it from the primary medulloblastoma." (PMID 30049282, 2018). "Our previous study has shown that a panel of 12 genes including ERCC1, hMLH1, ATM, CDKN2B (p15INK4B), p14ARF, CDKN2A (p16INK4A), RASSF1A, RUNX3, GATA6, NDRG2, PTEN, and RARβ might be useful in evaluation of glioma aggressiveness." (PMID 25648363, 2015). "Although deletions at the CDKN2A locus that includes ARF and INK4A commonly occur in human high-grade gliomas, gliomas have not been previously reported in mice deficient for p19Arf." (PMID 25423036, 2014). "Variants of the TERT and RTEL genes are predominantly associated with glioblastoma, whereas variants of the CDKN2A and EGFR genes are associated with overall glioma risk, not with a specific subtype." (PMID 23236348, 2012). "On the other hand, CDKN2A inhibits the CDK4/cyclin D1 complex and, in this way, the transition G1 → S. Hypermethylation-mediated silencing of RB1 and CDKN2A has been frequently observed in primary glioma tissues." (PMID 22778947, 2012). "For CDKN2A, 7 out of 12 glioma samples showed negative staining, possibly reflecting the fact that CDKN2A is often deleted in gliomas." (PMID 21365010, 2011). "However, these investigations have often focused on limited glioma subtypes and have not integrated a broader spectrum of molecular markers, such as CDKN2A/B deletions, which are now essential to the current diagnostic framework." (PMID 40507765, 2025). "Homozygous losses of CDKN2A/B or RB1 were seen in subgroups of patients, with homozygous RB1 deletions being enriched in H3 G34-mutant diffuse hemispheric gliomas when compared to IDH-wildtype glioblastomas and IDH-mutant gliomas from the GGN cohort (reference cohort 3)." (PMID 39842935, 2025). "Interestingly, a study of radiation-induced gliomas reported recurrent PDGFRA amplification and loss of CDKN2A/B in the absence of histone H3 or IDH1/2 mutations as diagnostic markers and potential targets for treatment." (PMID 41007286, 2025).
glioma (continued). "Additionally, heterozygous CDKN2A/B deletions in gliomas, detected in 17% of primary IDH-mut gliomas, hold prognostic significance akin to homozygous deletions, highlighting their relevance in glioma progression." (PMID 39593128, 2024). "When evaluating therapy strategies in these tumors, ruling out CDKN2A/B deletions might be indicated, as wait-and-scan strategies are not warranted in higher grade glioma." (PMID 39316316, 2024). "However, in a recent study that was conducted on 56 gliomas, 38 cases showed no expression with p16 and CDKN2A homozygous deletion with FISH." (PMID 39409918, 2024). "Notably, deletion, mutation or hypermethylation of CDKN2A/2B are frequently observed in head and neck cancer, non-small cell lung cancer (NSCLC), prostate adenocarcinoma (PRAD), glioma, esophageal carcinoma, bladder cancer and T-cell lymphoma." (PMID 38822443, 2024). "No CDKN2A homozygous deletion was identified in grade 2 gliomas." (PMID 36900302, 2023). "Hence, the preoperative, noninvasive MRI prediction of CDKN2A/B is of great value, as there are currently no clinically validated imaging-based markers for predicting CDKN2A/B homozygous deletion in gliomas." (PMID 37190513, 2023). "While some centres have started to manage IDH-mutant CDKN2A/B HD astrocytomas using the EORTC-NCIC protocol for IDH-wildtype glioblastomas, historically most of these cases would have been treated as lower-grade (Grade 2 and 3) gliomas with radiation therapy and sequential chemotherapy." (PMID 37504251, 2023). "This is highlighted by the adoption of CDKN2A/B HD as an essential criterion for astrocytoma and IDH-mutant central nervous system (CNS) WHO grade 4 in the fifth edition of the World Health Organisation (WHO) Classification of Central Nervous System Tumours (2021)." (PMID 37504251, 2023). "CDKN2A mutations represent a negative prognostic factor in terms of survival in both diffuse IDH-mutant and IDH-wildtype gliomas, with lower impacts on grade 2 and 3 gliomas than grade 4 gliomas." (PMID 36136867, 2022). "According to analysis of individual molecular markers, we found a significantly higher heme biosynthesis mRNA expression signature in gliomas with IDH wildtype (p < 0.0005), without 1p19q codeletion (p < 0.0005), with homozygous CDKN2A/B loss (p < 0.0005) and with EGFR amplification (p = 0.001)." (PMID 36187350, 2022). "Similarly, glioma patients without CDKN2A deletion also had better prognosis, compared with glioma patients with CDKN2A deletion." (PMID 33959491, 2021). "However, the connections between CDKN2A and EGFR in glioma are unclear." (PMID 33959491, 2021). "In the present study, using The Cancer Genome Atlas (TCGA), the Chinese Glioma Genome Atlas (CGGA), the Memorial Sloan Kettering Cancer Center (MSKCC), and Gene Expression Omnibus (GEO) datasets, the prognostic significance of EGFR and CDKN2A alteration was determined." (PMID 33959491, 2021). "Interestingly, CDKN2B, CDKN2A, MTAP, and KLHL9 also belonged to the largest community in the dysregulated ceRNA network, suggesting their possible role to inhibit the development of glioma together." (PMID 31719831, 2019). "Moreover, those gliomas exhibited significantly increased copy number alterations including recurrent focal amplifications of PDGFA and EGFR, as well as recurrent deletions of CDKN2A/B." (PMID 31428092, 2019). "We could not confirm the impact on OS of LOH of 9p21.3 (the CDKN2A region) which is frequently reported as a progression marker particularly in higher grade glioma." (PMID 29663171, 2018).